NUPR1 (nuclear protein 1, transcriptional regulator)
Diseases named in the same sentence as NUPR1 in open-access papers (continued):
Sharing a sentence is not in itself a finding about the gene and the disease.
glioma (9 papers, 2021 to 2026). A benign or malignant brain and spinal cord tumor that arises from glial cells (astrocytes, oligodendrocytes, ependymal cells). "In the future, we plan to employ genomics strategies, such as Ch-IP-Seq and microarrays, to identify additional targets of NUPR1 associated with autophagy and drug resistance in glioma cells." (PMID 37305393, 2023). "Additionally, NUPR1 has been implicated in glioma development by affecting cell cycle arrest." (PMID 37305393, 2023). "This is due to the evidence that NUPR1 promotes glioma cell autophagy and TMZ resistance via the KDM3A/TFEB axis." (PMID 41596413, 2026). "Overall, our findings highlight a mechanism by which NUPR1 enhances glioma cell autophagy and TMZ resistance via the KDM3A/TFEB axis." (PMID 37305393, 2023). "Collectively, these findings support the role of NUPR1 in promoting cell autophagy to reduce TMZ resistance in glioma in vivo via the KDM3A/TFEB axis." (PMID 37305393, 2023). "This study investigated the mechanism of NUPR1 in TMZ resistance in hypoxia-treated glioma cells and its mechanism in modulating autophagy." (PMID 37305393, 2023). "As expected, reduced NUPR1 and increased Nestin expression were observed in 3D collagen/FN cultured glioma cells, whereas blockade of integrin αvβ3 or CDC42 overexpression reversed the phenomenon." (PMID 33408794, 2021). "Together, these results suggested that the integrin αvβ3/CDC42/F-actin/YAP-1/NUPR1/Nestin signaling pathway was activated in 3D collagen/FN cultured glioma cells and induced glioma cell proliferation." (PMID 33408794, 2021). "Nuclear protein-1 (NUPR1) is a regulator of glioma progression." (PMID 37305393, 2023). "In a xenograft tumor model, silencing NUPR1 suppressed TMZ resistance in glioma cells in vivo." (PMID 37305393, 2023). "Collectively, these findings suggest that silencing NUPR1 could limit TMZ resistance in hypoxia-induced glioma cells." (PMID 37305393, 2023). "Our in vitro results demonstrated that 3D collagen/FN culture could induce the PI3K/AKT and CDC42/YAP/NUPR1 signal activation in glioma cells, resulting in growth factors SOX2/Nestin up-regulation." (PMID 33408794, 2021). "Therefore, we hypothesized that NUPR1 could maintain TMZ resistance in hypoxia-treated glioma cells by modulating autophagy." (PMID 37305393, 2023). "However, the specific role of NUPR1 on TMZ resistance in glioma cells through autophagy remains unclear." (PMID 37305393, 2023). "Additionally, whether NUPR1 could modulate other genes that participate in glioma cell autophagy and TMZ resistance under hypoxia remains unknown." (PMID 37305393, 2023). "Our results suggest that hypoxia-induced NUPR1 promotes TFEB transcription by binding to KDM3A and reducing H3K9me2 levels, thereby augmenting glioma cell autophagy and TMZ resistance." (PMID 37305393, 2023). "We found that hypoxia upregulated NUPR1 expression and autophagy while NUPR1 silencing suppressed hypoxia-induced TMZ resistance and autophagy in glioma cells." (PMID 37305393, 2023). "These genes include HMGA1 in glioma, AKT1 in glioma, PTC, GC, and HCC, HEMGN in PTC, APLN and MMP19 in GC, WNT1 in CRC, NUPR1 in CRC and OSCC, LY6E and CTSB in CHOL, KLK4 and PLXNB2 in OC, and HDAC4 and STAT3 in SaOS." (PMID 36175921, 2022). "miR-637 inhibits the growth of tumor cell lines and tumor growth in xenograft animal models by targeting AKT1 in glioma and PDAC, LIF in HCC, and NUPR1 in OSCC." (PMID 36175921, 2022). "Low expression of miR-637 leads to up-regulation of the expression levels of HEMGN in PTC, NUPR1 in OSCC, and AKT1 in glioma and PDAC, thereby activating the PI3K/AKT signaling pathway and inhibiting the reproduction and growth of cancer cells." (PMID 36175921, 2022). "Our study provided evidence suggesting that collagen and FN collaborate to facilitate proliferation and tumorigenesis of glioma cells through the PI3K/AKT/SOX2 and CDC42/F-actin/YAP-1/Nupr1/Nestin pro-survival signaling networks." (PMID 33408794, 2021).
glioma (continued). "We provided evidence that collagen/FN complex regulates glioma stemness via an integrin αvβ3-activated PI3K/AKT/SOX2 and CDC42/F-actin/YAP-1/Nupr1/Nestin signaling network." (PMID 33408794, 2021). "These miR-637-targeted genes include HMGA1, CDK6, and WNT7A in glioma, HEMGN in PTC, APLN in GC, USP21 in HCC, LY6E and CTSB in CHOL, NUPR1 in OSCC and MM, HDAC4 in SaOS, ABL1 in CML, KLK4 in OC, PLXNB2 in OC, AKT1 in TNBC, PTC, and HCC, AKT3 in TNBC, and RING1 in CCa." (PMID 36175921, 2022). "More importantly, we identified that collagen/FN stimulated glioma progression through integrin αvβ3-induced PI3K/AKT/SOX2 and CDC42/F-actin/YAP-1/Nupr1/Nestin double signal activation simultaneously, expounding the underlying mechanism of the extracellular matrix-induced tumor signaling network." (PMID 33408794, 2021). "However, we did not probe the role of NUPR1 in the resistance of glioma cells to other chemotherapeutic drugs." (PMID 37305393, 2023). "Moreover, NUPR1 expression was notably up-regulated in hypoxia-treated U251-TMZ and T98G-TMZ cells, thus eliciting a potential role of NURP1 in mediating TMZ resistance in hypoxia-treated glioma cells." (PMID 37305393, 2023). "We identified the integrin αvβ3/CDC42/F-actin/YAP-1/Nupr1/Nestin signaling pathway, which was independent of the PI3K/AKT signaling in 3D collagen/FN cultured glioma cells." (PMID 33408794, 2021).
multiple myeloma (9 papers, 2019 to 2023). "Existing studies have shown that NUPR1 suppression decreased autophagy and increased the apoptotic rate in multiple myeloma, but rapamycin reversed this increase." (PMID 37305393, 2023). "MiR‐637 promotes apoptosis and suppresses cell proliferation and autophagy in multiple myeloma by targeting NUPR1." (PMID 33332746, 2021). "Here, our results indicate that TFP targets NUPR1, inhibiting cell growth and inducing apoptosis by autophagy inhibition in multiple myeloma cells." (PMID 32810364, 2020). "NUPR1, also known as p8 and a candidate of metastasis 1, is a transcriptional coregulator that plays regulatory roles in various types of malignant tumors, including pancreatic cancer, multiple myeloma, and bladder cancer." (PMID 33976960, 2021).
prostate carcinoma (9 papers, 2018 to 2025). A carcinoma that arises from epithelial cells of the prostate gland. "The expression of NUPR1 was negatively associated with invasiveness and tumor progression in prostate cancer." (PMID 36468653, 2023). "NUPR1 was able to inhibit tumor progression in brain and prostate cancers, as well as being overexpressed in several other cancers." (PMID 30042885, 2018). "Also, NUPR1 expression was attenuated in human prostate cancer cells." (PMID 36468653, 2023). "Nuclear protein 1 (NUPR1), a stress-induced protein, has been found to represent an intriguing link between cellular and ER stress, which plays an essential part in the development of a number of malignancies, including pancreatic, breast, and prostate cancers." (PMID 37854285, 2023).
bladder cancer (7 papers, 2021 to 2026). "NUPR1, a nuclear protein, plays a critical role in redox reactions, and macrophages have been implicated as the most relevant immune cells associated with NUPR1 expression in bladder cancer." (PMID 38167084, 2024). "NUPR1 is a pro-tumorigenic factor in bladder cancer (BLCA), but the mechanisms governing its protein stability remain poorly defined." (PMID 41998836, 2026). "We hope to provide a new strategy for the future development of bladder cancer drug therapy by exploring the biological function of NUPR1 in BLCA." (PMID 36468653, 2023). "Nevertheless, the molecular mechanism of NUPR1 in bladder cancer (BLCA) remains unclear." (PMID 36468653, 2023).
colon cancer (7 papers, 2014 to 2026). "Indeed, functional alterations in Nupr1 have been associated with several malignancies including breast, cholangiocarcinoma, colon cancer, prostate, bladder and lung." (PMID 24902898, 2014). "In a previous study, the expression level of NUPR1 was negatively correlated with the grade of colon cancer, and the expression of NUPR1 was lower in high-grade colon cancer tissues than in normal tissues." (PMID 35600351, 2022). "Blockage of NUPR1 might be as a potential therapeutic strategy for stage II-III CDX2-positive colon cancer." (PMID 41820294, 2026). "Blockage of NUPR1 might be as a potential therapeutic strategy for CDX2-positive stage II-III colon cancer." (PMID 41820294, 2026). "In addition, miR-2277-3p promotes colon cancer migration and invasion by targeting NUPR1." (PMID 38791180, 2024). "Recent reports have shown that aurora kinase A (AURKA), IL6R, NUPR1, and DICER1 play important role in the development, progression, and metastasis of a variety of cancers including colon cancer." (PMID 36685857, 2022).
melanoma (7 papers, 2012 to 2024). A malignant, usually aggressive tumor composed of atypical, neoplastic melanocytes. "IDPs, such as nuclear protein 1 (NUPR1), have been targeted to successfully treat melanoma cell lines." (PMID 34681018, 2021). "Using microarrays to screen for potential factors, we have identified nuclear protein 1 (Nupr1) that is markedly reduced in the TRCs in 3D soft fibrin matrices when compared with melanoma cells on 2D rigid plastic." (PMID 27089143, 2016). "To determine the functional role of Nupr1 in melanoma cells, we altered Nupr1 levels and assayed melanoma cell proliferation." (PMID 27089143, 2016). "Silencing Nupr1 in 2D melanoma cells elevated the number of mice with tumors (from 9 out of 16 mice to 12 out of 16 mice); overexpressing Nupr1 in TRCs significantly suppressed the number of mice with tumors (from 15 out of 16 mice to 9 out of 16 mice)." (PMID 27089143, 2016). "To further explore the role of Nupr1 in vivo, we either silenced Nupr1 in melanoma cells grown on 2D rigid plastic (whose Nupr1 levels were high) or overexpressed Nupr1 in TRCs (whose Nupr1 levels were low) and injected those treated cells into mice at 2000 cells per mouse subcutaneously." (PMID 27089143, 2016). "On the other hand, three genes (MAFB, NUPR1, and SLC1A3), which were upregulated following combination therapy, showed low expression in the melanoma TCGA cohort." (PMID 38594618, 2024). "To determine the role of nuclear YAP in Nupr1, we performed chromatin immunoprecipitation (ChIP) assay and found that YAP was enriched by 7- to 10-folds at Nupr1 promoter sites for melanoma cells on 2D rigid plastic." (PMID 27089143, 2016). "Similar to melanoma, PDAC presented with xeno-cannibal activity towards living lymphocytes (60 ± 1.88% CFSE+ cells), although this was unaffected by Nupr1-depletion and TGFβ treatment." (PMID 22821859, 2012).
osteosarcoma (7 papers, 2019 to 2025). A usually aggressive malignant bone-forming mesenchymal neoplasm, predominantly affecting adolescents and young adults. "In the study of quercetin-induced osteosarcoma cell death, quercetin promoted the expression of autophagy-related genes through activation of NUPR1 gene activity, which subsequently triggered excessive autophagy in cancer cells." (PMID 36467088, 2022). "For example, by increasing ROS levels, quercetin can induce the expression of NUPR1 and activates autophagy in osteosarcoma cells." (PMID 34359572, 2021). "A study of quercetin in osteosarcoma cells revealed it activates autophagic flux via its action on nuclear protein 1 (NUPR1) which is involved in autophagosome formation, cargo degradation, and autophagosome-lysosome fusion." (PMID 33435480, 2021). "Specifically, quercetin increased NUPR1 expression and activated of NUPR1 reporter activity, which contributed to the expression of autophagy-related genes and subsequent initiated autophagic cell death in osteosarcoma cells." (PMID 33041510, 2020). "Furthermore, it has been demonstrated that quercetin upregulates NUPR1 expression and induces ROS-NUPR1-dependent autophagic cell death in osteosarcoma cells." (PMID 39991577, 2025).
acute pancreatitis (6 papers, 2014 to 2023). An acute inflammatory process that leads to necrosis of the pancreatic parenchyma. "NUPR1, known as p8, was first described in pancreatic acinar cells of rats in a study evaluating molecular changes caused by acute pancreatitis." (PMID 33920455, 2021). "NUPR1 is a crucial stress response transcription factor first identified to be activated in acute pancreatitis." (PMID 36468653, 2023). "Congruent with a role of NUPR1 in cell death by necrosis in acute pancreatitis, Nupr1-KO mice displayed a higher necrosis as well as necrotic score when compared with wild type littermates." (PMID 30451898, 2018). "Altogether, these results strongly suggest that induction of NUPR1 during acute pancreatitis controls both, inflammation and necrosis, by two different and complementary mechanisms." (PMID 30451898, 2018). "Finally, in vivo experiments, using acute pancreatitis which induces ER stress as well as NUPR1 activation, we observed that NUPR1 expression protects acinar cells from necrosis in mice." (PMID 30451898, 2018).
pancreatic adenocarcinoma (6 papers, 2019 to 2023). "A study in pancreatic adenocarcinoma has suggested that TFP binds to NUPR1 through the region around amino acid Thr68, indicating that TFP could act as an NUPR1 inhibitor." (PMID 32810364, 2020).
COVID-19 (5 papers, 2020 to 2022). A disease caused by infection with severe acute respiratory syndrome coronavirus 2. "Upstream regulator analysis identified five key regulators after exposure to COVID-19 in our study, one phosphatase (PDCD1), 3 transcriptional regulators (E2F3, NUPR1 and LARP1) and one mitotic spindle protein (CKAP2L)." (PMID 35547542, 2022). "This module included the NUPR1 stress response gene as well as CSTB, which is an inhibitor of cathepsins like CTSL and CTSB that are involved in COVID-19 viral entry." (PMID 35007307, 2022).
triple-negative breast carcinoma (5 papers, 2024 to 2025). An invasive breast carcinoma which is negative for expression of estrogen receptor (ER), progesterone receptor (PR), and human epidermal growth factor receptor 2 (HER2). "Specifically, WTAP elevates Lipocalin 2 expression by enhancing nuclear protein 1 (NUPR1) m6A methylation, thereby repressing ferroptosis and facilitating triple-negative breast cancer progression." (PMID 40986143, 2025).
non-small cell lung carcinoma (4 papers, 2016 to 2024). A group of at least three distinct histological types of lung cancer, including non-small cell squamous cell carcinoma, adenocarcinoma, and large cell carcinoma. "Nuclear protein 1 transcription regulator (NUPR1, also called candidate of metastasis 1) has been implicated in progression of pancreatic, bladder, liver and non small cell lung cancers." (PMID 28957348, 2017). "Downregulation of NUPR1 gene expression can limit the growth of human non-small cell lung cancer in vivo and in vitro." (PMID 39165641, 2024). "Downregulation of Nupr1 expression significantly inhibited non-small cell lung cancer H1299 cell proliferation and colony formation in vitro." (PMID 27285315, 2016). "Moreover, knockdown of Nupr1 by lentivirus-mediated RNAi significantly inhibited colony formation of human non-small cell lung cancer H1299 in vitro and tumor growth in vivo by tail vein injection of shRNA against Nupr1." (PMID 27285315, 2016).
ovarian carcinoma (4 papers, 2016 to 2023). A malignant neoplasm originating from the surface ovarian epithelium. "The purpose of our study was to explore the expression of NUPR1 in each cell population in ovarian cancer." (PMID 37124501, 2023). "RT-qPCR analysis revealed that URI1, PAK2, PARP1, CLU, and TIMP3 were significantly upregulated, while UBB, RPL11, CAV1, NUPR1, and Hsp90ab1 were significantly downregulated in the ovarian cancer samples." (PMID 37124501, 2023). "We also found that apoptosis-related genes, URI1, PAK2, PARP1, CLU and TIMP3, were highly expressed, while immune-related genes, UBB, RPL11, CAV1, NUPR1 and Hsp90ab1, were lowly expressed in ovarian cancer cells." (PMID 37124501, 2023). "NUPR1 may affect ovarian cancer proliferation and invasion by signaling through the AKT pathway." (PMID 37124501, 2023).
clear cell renal cell carcinoma (3 papers, 2021 to 2023). "Depletion of NUPR1 suppressed tumorigenesis and sensitized clear cell renal cell carcinoma to sorafenib treatment in vivo." (PMID 34359572, 2021).
Obesity (3 papers, 2019 to 2024). Accumulation of substantial excess body fat. "Elevated expression of NUPR1 has been associated with a high-fat diet, and it has been suggested that NUPR1 can protect tissues from cell injury in the context of obesity and a high-fat diet." (PMID 36307402, 2022). "Recent studies suggest NUPR1 protects tissues from cell injury in the context of obesity and high-fat diet." (PMID 36307402, 2022). "Also, NUPR1 is related to the degradation of insulin storages and subsequent secretion during inflammatory and obesity-related tissue stress." (PMID 39102232, 2024).
astrocytoma (2 papers, 2016 to 2017). "Increased expression of Chop and induction of apoptosis in response to ERS have been associated with Nupr1 activation in astrocytoma cells exposed to cannabinoid, so we assessed the effect on Chop expression after silencing Nupr1." (PMID 27031958, 2016). "Upregulated expression of CHOP and induction of apoptosis in response to ER stress have been related to Nupr1 activation in astrocytoma cells exposed to cannabinoid." (PMID 28694771, 2017).
endometrial cancer (2 papers, 2017 to 2021). Primary or metastatic malignant neoplasm involving the endometrium (mucous membrane that lines the endometrial cavity). "Similarly, ETV5 induces the epithelial–mesenchymal transformation of endometrial cancer through transcriptional activation of the nidogen-1 (NID1) and nuclear protein 1 (NUPR1) genes, participating in the process of endometrial cancer invasion." (PMID 34736492, 2021).
heart failure (2 papers, 2018 to 2021). Inability of the heart to pump blood at an adequate rate to meet tissue metabolic requirements. "Recent evidence indicates that Nupr1 activation contributes to cardiac fibrosis, while protecting against autophagy and apoptosis that lead to heart failure." (PMID 29556499, 2018).
metastatic cancer (2 papers, 2025). A carcinoma which has spread from the original site of growth to another anatomic site. "Additionally, NUPR1 is linked to BM in LSCC, and NEAT1 is a potential metastatic cancer cell cycle participant." (PMID 39085744, 2025). "However, immunohistochemistry revealed significant upregulation of NUPR1 in metastatic cancer tissues compared to adjacent normal tissues." (PMID 39085744, 2025). "NUPR1, a multifunctional transcriptional regulator, is also referred to as COM1 due to its expression in metastatic cancer cells." (PMID 39748602, 2025).
osteoarthritis (2 papers, 2020 to 2025). A noninflammatory degenerative joint disease occurring chiefly in older persons, characterized by degeneration of the articular cartilage, hypertrophy of bone at the margins and changes in the synovial membrane. "•ATF4 transcriptionally activates NUPR1, offering a novel therapeutic strategy to mitigate ferroptosis and slow osteoarthritis progression." (PMID 40782567, 2025). "Thus, it is likely that NUPR1 represents one of several important mediators, rather than the sole effector of ATF4′s actions in osteoarthritis." (PMID 40782567, 2025).